STAT3 (signal transducer and activator of transcription 3)
Diseases named in the same sentence as STAT3 in open-access papers (continued):
Sharing a sentence is not in itself a finding about the gene and the disease.
colon carcinoma (continued). "Here, we showed that chitosan significantly increased the phosphorylation of STAT3 in Huh7 HCC cells but not in HT29 colon cancer cells." (PMID 28367998, 2017). "In colonic tumors, lack of vanin-1 is associated to higher levels of PPAR and to a reduction in IL-6 production and STAT3 activation, whose levels correlate with tumor size." (PMID 28448444, 2017). "Pharmacological inhibition of STAT3 was able to reduce muscle atrophy in mice with colon carcinoma; however, it was not sufficient to completely attenuate cachexia." (PMID 26856534, 2016). "Moreover, thymoquinone blocked STAT3 signaling via inhibition of Janus kinase (JAK) 2- and Src-mediated phosphorylation of EGFR tyrosine kinase, thus inducing apoptosis in human colon cancer cells." (PMID 27529277, 2016). "Whereas IL-6 induced STAT3 phosphorylation in the colonic cancer cell lines, primary non-malignant intestinal organoids did not respond to IL-6 classic signalling." (PMID 27869785, 2016). "Lee and colleagues found that the standard CD44 expressed in the nucleus could reprogram colon cancer cells line to CSCs under suspension culture, CD44 could integrate with STAT3 and gp130 after reprogramming and function as a transcription factor complex." (PMID 26540347, 2015). "In conclusion, (E)-4-(3-(3,5-dimethoxyphenyl)allyl)-2-methoxyphenol could inhibit cell growth of colon cancer in vivo and in vitro through activation of Fas, DR3 and inhibition of STAT3 and NF-κB pathways." (PMID 26474284, 2015). "The HT-29 colon carcinoma cell line used in our laboratory does not express an endogenous functional IL-26R and induces only minimal STAT3 phosphorylation after IL-26 stimulation." (PMID 23875025, 2013). "Based on the differences found, new hpdODNs were designed and tested for their STAT3/STAT1 discrimination ability by measuring SW480 colon carcinoma cell death and absence of inhibition of STAT1-dependent IFNγ-induced cell death." (PMID 22423663, 2012). "To confirm the inhibition of phosphorylated or activated STAT3 by GO-Y030 in colon cancer cells, we examined STAT3 phosphorylation (Y705) in three independent colon cancer cell lines (cells were cultured in 10% FBS) using phospho-STAT3 (Tyrosine 705) antibodies." (PMID 21694723, 2011). "Here, Stattic and WP1066 were used as positive control to detect their effects on apoptosis in HCT116 colon cancer and U266 multiple myeloma cells, which conformed the JAK2/STAT3 pathway may be an important target to induce the apoptosis of cancer cells." (PMID 20712901, 2010). "Drug-induced tyrosine phosphorylation of JAK2 and Src attenuated EGFR and STAT3 tyrosine phosphorylation, but EGFR tyrosine kinase inhibitor therapy (gefitinib) suppressed STAT3 phosphorylation in HCT116 colon cancer cells without influencing JAK2 or Src phosphorylation." (PMID 38397437, 2024). "However, while STAT3 activation is a necessary condition for colon tumor development, it is not enough to trigger colon tumors solely through ETBF." (PMID 39483461, 2024). "In addition, the disruption of PTK6 in mice impaired STAT3 activation and protected animals from AOM/DSS-induced colon cancer, indicating that this substrate could be a key mediator for PTK6’s role in DNA damage-induced CRC." (PMID 37509364, 2023). "An inhibitor of Stat3 phosphorylation encouraged morphological changes in KNC, colon cancer-type cells like those in kaempferol-treated cells, signifying that kaempferol-induced differentiation might be arbitrated by means of inhibition of Stat3 phosphorylation." (PMID 37239974, 2023). "In order to investigate whether the PCNP mediated STAT3/5 signaling pathway is involved in the pathogenesis of colon cancer, we transfected HCT166 and SW480 cells with sh-NC and sh-PCNP, followed by treatment with DMSO and 1 μm colivelin (STAT3 activator) for 24 h." (PMID 35468892, 2022).
colon carcinoma (continued). "Monotherapy with Ab27 significantly decreased tumor growth in liver and colon cancer xenograft models, including a sorafenib-resistant model, and decreased the phosphorylation of focal adhesion kinase (FAK), p27Kip1, and signal transducer and activator of transcription 3 (STAT3)." (PMID 35211652, 2022). "In contrast to MDA-MB-231 tumor cell lines, STAT3 plays no major role in the colon carcinoma cell line HT-29 and it could explain the lower effects of the new compounds on this cell line." (PMID 34066442, 2021). "A previous study showed that a lack of STING signaling could not limit STAT3, NF-κb pathway activation, thereby exacerbating colitis and inducing colon cancer in colitis mice." (PMID 34829556, 2021). "To examine whether elevated CREPT level correlates to the expression of STAT3-downstream genes, we analysed the messenger RNA (mRNA) levels of several key genes including c-MYC, CCND1 and Bcl-XL in breast and colon cancers from The Cancer Genome Atlas RNA-sequencing database." (PMID 33531691, 2021). "Furthermore, the data reported here show that LPE is able to inhibit the rIL-6-dependent cell migration and invasiveness in human primary T88 and T93 colon cancer cells via the up-regulation of MMP-2 expression, and that the observed effects correlate with the STAT3 phosphorylation levels." (PMID 34885656, 2021). "While the role of P2 × 7 receptor-mediated STAT3 signaling in colon cancer has not been reported." (PMID 33330466, 2020). "However, there is no report on the effect of P2 × 7 receptor-mediated STAT3 signaling in colon cancer cells." (PMID 33330466, 2020). "Taken together, our results revealed that propofol could promote apoptosis and inhibit invasion, mainly through its inhibition on STAT3 and HOTAIR to deactivate Wnt signaling pathway by increasing WIF‐1 expression levels, which might serve as a therapeutic role for colon cancer." (PMID 31953926, 2020). "However, the correlation between HNF3β and STAT3 signal pathway has not been well documented and no related study was conducted in colon cancer." (PMID 31696055, 2019). "However, although all the tested colon cancer cell lines were responsive to IFN-γ, as revealed by induction of ISGs14, 15 such as STAT-1, STAT-3, interferon responsive factor (IRF-1), and BCLXL, unexpectedly MMP-1 mRNA levels were reduced following IFN-γ treatment (18 h)." (PMID 28819304, 2017). "In summary, this study showed that fasting could induce autophagy of colon cancer cells and then downregulate the level of adenosine, which increased M2 polarization of TAMs through inactivating JAK1/STAT3, and eventually inhibitted tumor growth by promoting antitumor immunity in vitro and in vivo." (PMID 29088814, 2017). "Taken together, our results suggest the induced STAT3 activation as a possible mechanism for the resistance to MEK inhibitor and demonstrate the potentials of a combination therapy using MEK and STAT3 inhibitors in pancreatic and colon cancers harboring K-Ras mutant proteins." (PMID 25961376, 2015). "In order to further investigate the involvement of the JAK/STAT pathway in enhancing colon cancer cell survival and the mechanism of RKIP phosphorylation, we examined whether JAK 1 and 2 overexpression could stimulate STAT3 activation and thereby negate the inhibitory effects of CPT." (PMID 24098947, 2013). "No report has been published to target STAT3 in colon cancer-initiating cells or colon stem cells." (PMID 21694723, 2011).
colon carcinoma (continued). "In addition, ADAM17 also promotes STAT3 activation by induction of EGFR/IL-6 transduction signaling pathways, which ultimately lead to tumor progression; inhibition of the ADAM17/IL-6/STAT3 signaling axis significantly attenuated the growth of colon cancer cells." (PMID 36466812, 2022). "These transcriptional signatures are mainly involved in immune regulation (CEBPB, STAT3, and JAK2), metabolism (PPARGC1 and MTOR), cell cycle (CDK1), and apoptosis (BCL2), suggesting that the deregulation of these pathways in CTS may contribute to the altered prognosis in colon cancer." (PMID 31186640, 2019). "Furthermore, we demonstrated that chitosan might activate canonical Wnt/β-catenin-CD44 axis signaling in CD44positive colon cancer cells and noncanonical Wnt-STAT3 signaling in CD44negative HCC cells." (PMID 28367998, 2017). "However, it has been shown that STAT3 does not affect IL-18BP expression in colon carcinoma cells." (PMID 22761702, 2012). "Likewise, bazedoxifene treatment of human colon cancer cells harboring mutant APC did not reduce aberrant canonical WNT signaling, but suppressed IL11‐dependent STAT3 signaling." (PMID 30885958, 2019). "HCT-116 colon cancer cells were treated with CPT, OXP, and IL-6 separately or in combination in a time and dose-dependent manner and examined for phosphorylated and non-phosphorylated RKIP and STAT3 via Western blot analysis." (PMID 24098947, 2013). "Among the upstream regulators (TFs, kinases, and MMTRs) of the DEGs, the expression of STAT3, RPS6KA5, IKBKE, ERBB2, MTOR, and NFKB1 had a positive correlation with OS in colon cancer, while the expression of CDK1, CDK5, and BRD2 had a negative correlation with OS in colon cancer." (PMID 31186640, 2019). "Here, our additional assays showed that JAK/STAT3 signaling inhibitor AG490 at 50 μM, unlike α-hederin, failed to repress the viability of SW620 cells, suggesting that the JAK2/STAT3 signaling might specifically regulate the EMT of colon cancer cells." (PMID 30363706, 2018).
colitis (513 papers, 2010 to 2026). Inflammation of the colon. "The inhibition of the STAT3 pathway can significantly reduce the incidence of colitis-associated CRC." (PMID 41281755, 2025). "Here authors show that the ubiquitin ligase Pellino1 increases the activation of STAT3 in colitis and colitis-associated colon cancer, and these inflammatory conditions are mitigated upon monocyte-specific genomic deletion of Pellino1 in mice." (PMID 39893188, 2025). "This disruption of USP5-mediated STAT3 stability led to increased STAT3 ubiquitination, reduced STAT3 expression, and ultimately inhibited the progression of colitis-associated cancer transformation." (PMID 41281755, 2025). "The Pellino1-STAT3 axis plays a pivotal role in modulating the pathogenesis of colitis and CAC through the K63-linked ubiquitination of STAT3." (PMID 39893188, 2025). "Further, this study demonstrates the aggravation of DSS-induced colitis by intestinal epithelial cell-specific knockout Stat3 in mice, while Stat3 overexpression by adeno-associated virus attenuates colitis in DSS-induced Usp25−/− mice." (PMID 39773987, 2025). "IHC analysis also revealed that administration of α-hederin reversed AOM/DSS-induced STAT3 and phosphorylated STAT3 expression, indicating that α-hederin suppresses the development of colitis-associated tumors." (PMID 41281755, 2025). "IL-22, produced by CD11c+ cells in a murine colitis model, stimulates organoid growth from wild-type mouse intestinal crypts, while Stat3-deficient crypts fail to generate organoids." (PMID 39860613, 2025). "miR-93-5p, an IL-6-driven G-MDSC exosome, promotes the differentiation of M-MDSCs into M2 macrophages and is implicated in the STAT3 signaling mechanism that promotes the transition from colitis to cancer." (PMID 39990210, 2025). "Triptolide has been shown to alleviate colitis in IL-10-deficient mice by inhibiting the IL-6/STAT3 and IL-17 signaling pathways." (PMID 41476955, 2025). "Apigenin treatment inhibited colon damage, MPO activity, and the production of IL-1β, TNF-α, and IL-6 in DSS-induced colitis, as well as the NF-κB and STAT3 pathways in colitis-associated colon cancer tissues in mice." (PMID 39451206, 2024). "Reports have suggested that STAT3 regulates intestinal homeostasis, and mice with specific deletion of STAT3 in intestinal epithelial cells are more susceptible to experimental colitis, with downregulation of injury repair-related pathways." (PMID 39630809, 2024). "Knockout GNAI1 and GNAI3 in BMDSCs cells can induce phosphorylation of JAK2 and STAT3, promoting colitis-associated tumors in mice." (PMID 39695099, 2024). "Considered together, these data suggest that CSCC-induced inhibition in colitis is closely associated with the suppression of the STAT3/NLRP3 signaling pathway." (PMID 39329121, 2024). "Dysregulated STAT3 signaling has been implicated in the development of colitis-associated colorectal cancer (CA-CRC), a severe complication of long-standing IBD." (PMID 39187810, 2024). "The most studied ADAMs in IBD was Adam17, associated with EGFR and STAT3 signaling pathways crucial for the pathogenesis of colitis, high epithelial expression of which positively correlated with cell proliferation and goblet cell number in UC patients." (PMID 36901742, 2023). "It has been observed that IL-6 can induce the phosphorylation of STAT3, and the upregulation of phosphorylated STAT3 is implicated in the pathogenesis of colitis, emphasizing the critical role of STAT3 in colitis development." (PMID 37375369, 2023). "Mice with reduced STAT3 activity were highly susceptible to colitis by regulating the IL-6ST/gp130 cytokine receptor, which plays a key role in promoting intestinal barrier function and epithelial regeneration." (PMID 37875976, 2023). "STAT3 activation induced by IL-6 is critical in colitis-associated CRC growth and is known as the main mediator of EMT induction." (PMID 37047623, 2023).
colitis (continued). "In animal models, STAT3 activation in intestinal epithelial cells is required for wound healing, but also leads to the development of colitis-associated cancer in chronic inflammation." (PMID 37175705, 2023). "In a study, feeding mice with a Lactobacillus acidophilus led to the alleviation of colitis-associated inflammatory responses related to the IL-23/Th17 pathway through inhibition of STAT3 and secretion of IL-17." (PMID 37834058, 2023). "In mouse models of colitis-associated colon cancer, PPARβ/δ increased IL-6 expression and phosphorylation of STAT3, promoting tumorigenesis, while the concomitant 15-lipoxygenase-1 in colon epithelial cells inhibited these effects by downregulating PPARβ/δ." (PMID 37251321, 2023). "Futhermore enhanced susceptibility to experimental colitis has also known to occur in mice that have STAT3 genetically deleted in enterocytes." (PMID 37296943, 2023). "CD73-expressing ERCs inhibited the antigen presentation and stimulatory function of DCs associated with the STAT-3 pathway, which exerted a potent therapeutic effect against colitis." (PMID 37180168, 2023). "The characterization of the IL-6/GMDS-AS1/HuR/STAT3 axis provides a new perspective for understanding the pathogenesis of colitis-associated CRC and a novel diagnostic and therapeutic target in CRC." (PMID 36849492, 2023). "This modulates the activation of NF-κB and STAT3 in macrophages and colonic tissues, thereby influencing the onset of colitis and colitis-associated tumorigenesis." (PMID 38288125, 2023). "For instance, the aberrations of miRNAs can modulate STAT3 or NF‐κB activity simultaneously by targeting the members of JAK/STAT3 and NF‐κB pathways, which can promote or suppress the colitis or colitis‐associated tumourigenesis." (PMID 37138536, 2023). "For example, genetic deletion of STAT3 in mouse myeloid cells (neutrophils and macrophages) or in enterocytes resulted in increased severity and susceptibility to experimental colitis suggesting that STAT3 in these two cell lineages was protective against IBD." (PMID 36498596, 2022). "Recently, Fam64a has been reported to interact with Stat3, and to stimulate its transcriptional activity during colitis-associated carcinogenesis." (PMID 35602953, 2022). "Our current work focused on the role of STAT3 activation (in COL1+) fibroblasts in the AOM/DSS mouse model mimicking colitis-associated CRC, which is a well-known long-term complication of chronic colitis in inflammatory bowel diseases." (PMID 35326623, 2022). "Consistent with previous investigations, our results showed that BBR can inhibit inflammatory-associated mediators’ expression by dampening the JAK2/STAT3 signaling activation in cats with DSS-induced colitis." (PMID 36287004, 2022). "A recent study showed that miR-148a inhibited colitis and colitis-associated tumorigenesis via suppression of signaling of STAT3 and NF-κB, which are inflammation-associated factors." (PMID 34980190, 2022). "Stat3 activation has also been associated with ETBF-associated colitis and colonic tumour development in mice." (PMID 35468857, 2022). "Enterotoxigenic B. fragilis triggered colitis-associated colon carcinogenesis by stimulating signal transducer and activator of transcription 3 (STAT3)-mediated T helper 17 (Th17) responses." (PMID 35280689, 2022). "STAT3, which plays a key role in maintaining the intestinal mucosal barrier, is an important transcription factor that causes the onset of colitis." (PMID 36619196, 2022). "In mice with dextran sulfate sodium (DSS)-induced colitis, Reg3γ protein expression was upregulated and the STAT3-associated cytokines (such as IL-6, IL-17, and IL-22)/Reg3γ axis played a pivotal role in the acute phase of colitis." (PMID 34811636, 2022). "Collectively, these results suggest that the enhanced colitis-associated tumorigenesis caused by Phd2 haplodeficiency is mediated, at least in part, by activation of the STAT3 and ERK1/2 signaling pathways in tumor cells through EREG." (PMID 36509284, 2022).